MTOR (mechanistic target of rapamycin kinase)
Diseases named in the same sentence as MTOR in open-access papers (continued):
Sharing a sentence is not in itself a finding about the gene and the disease.
cancer (continued). "These ATP-competitive inhibitors compete for the ATP binding pocket on both mTOR and PI3K kinases, and it was hoped that a broader anti-cancer effect could be achieved with this dual targeting." (PMID 35582282, 2019). "In a pan-cancer proteogenomic analysis of thousands of human cancers, many of these cancers had high mTOR pathway activity despite the lack of alterations in canonical genes associated with this pathway." (PMID 31817676, 2019). "The oncogenic signalling RAS/RAF/ERK and PI3K/AKT/mTOR (mammalian target of rapamycin), regulate several key-players of the Pol I complex such as RRN3, UBF, and SL-1, resulting in the enhancement of rRNA synthesis in cancer." (PMID 31527430, 2019). "Under normoxia, mitochondrial metabolism in cancer cells may be favored because mTOR triggers mitochondrial biogenesis through TFAM and PGC1-α activation; in addition, mTOR may upregulate glycolysis through HIF-1α activation." (PMID 31600993, 2019). "However, it has been shown that mTOR is involved in TGF-β1 induced proliferation in several types of cells, such as fibroblasts and cancer cells, and activation of AMPK also inhibits these cells proliferation by suppressing mTOR activity." (PMID 29483552, 2018). "Since the metabolic features of cancer cells have repeatedly found to be linked with their infiltrative growth and with neoplastic progression, it seems reasonable to hypothesize that stimulation of the mTOR/LDH-A axis in non-tumor cells can result in a significant step towards neoplastic change." (PMID 30138330, 2018). "Another possible solution is not to target mTOR at all, but instead to exploit vulnerabilities within those cancers that have an mTOR-driven oncogenic signature." (PMID 29301334, 2018). "Based on the inhibited activity of the mTOR pathway in PSMD7 knockdown ESCC cell line, whether the anti‐cancer effect of PSMD7 knockdown in vivo through mTOR/p70S6K inhibition was evaluated." (PMID 29632807, 2018). "Given the importance of PI3K/AKT/mTOR signaling in the development of human cancers, the inhibitory function of JNU-144 towards cell growth and proliferation may be attributed to its suppression of mTOR activation." (PMID 30177727, 2018). "Data also suggest that mTOR inhibition with a dual PI3K/mTOR inhibitor, NVP-BEZ235, may revert chemoresistance in other types of cancer." (PMID 29805774, 2018). "Active-site dual mTORC1 and mTORC2 inhibitors (asTORi) have been developed for superior mTOR inhibition and anti-cancer potency but have not been studied in the context of oncolytic viral infection." (PMID 30138450, 2018). "However, other mechanisms for urolithin-mediated anti-cancer effects have been proposed, such as PI3K/AKT/mTOR and AR receptor." (PMID 30501068, 2018). "Data from publicly available large-scale sequencing studies have shown that genetic alterations in drug targets, cell death and major cancer driving pathways, e.g., PI3K/AKT/MTOR or RAS/MAPK, and nuclear receptors can be found across all cancer types; however, at highly variable frequencies." (PMID 30545124, 2018). "Taking advantage of the availability of several inhibitors of PI3K/mTOR signaling pathway developed as cancer drugs, we specifically evaluated the effect of Everolimus (mTOR inhibitor) MK2206 (Akt inhibitor) and BEZ235 (double mTOR/PI3K inhibitor) on our models." (PMID 29352118, 2018). "Aberrantly activated PI3K/AKT/mTOR signaling pathway is known to play a central role in aerobic glycolytic reprogramming, tumor growth, and survival, and a cross-talk between PI3K/AKT/mTOR signaling and O-GlcNAcylation has been observed in several cancers." (PMID 30356686, 2018). "The AKT/mTOR signalling pathway has been reported as a negative sensor in autophagy regulation; the phenomenon has been demonstrated in various different cancer cells." (PMID 29587684, 2018).
cancer (continued). "Several drugs targeting nodes of the two pathways have been developed, and three representative agents (PI3k/mTOR dual inhibitor BEZ235, mTORC1 inhibitor everolimus, and MEK inhibitor AZD6244) FDA-approved for the treatment of various cancers were used in our work." (PMID 29374144, 2018). "Increased levels of both Akt and mTOR have been observed in tumors; however, driving mTORC1 activity alone is not sufficient for cancer progression in cells due to the possible negative feedback on Akt from downstream mTOR targets." (PMID 29789464, 2018). "Together, these data are in line with other studies that suggest upregulation of pAMPK, REDD1, and inhibition of mTOR activity does not correlate with metformin sensitivity in cancer cell lines." (PMID 29423103, 2018). "mTOR is a downstream target of EGFR signaling and therefore considered as an important therapeutically attractive target for the treatment of various types of cancer." (PMID 30154572, 2018). "Moreover, in this study, we also found that several cancer-related pathways, such as cell cycle, IGF1/mTOR and Fas pathways, were related to three-gene signature." (PMID 29910195, 2018). "While many pan-PI3K or PI3K/mTOR inhibitors have demonstrated poor clinical safety profiles, several recent phase I clinical trials testing TOR-KIs compounds have reported acceptable safety and preliminary activity in patients with relapsed/refractory cancers." (PMID 29464092, 2018). "Overall, such studies highlight the importance and potential of targeting the mTOR survival pathway, suggesting that co-treatment of cisplatin and mTOR inhibitors, such as Torin2, may be beneficial for the management of EOC and various other resistant cancers." (PMID 29642900, 2018). "The formation of nanochannel structures between cancer cells have been widely studied and seems to rely on the mTOR pathway, evidenced through the marked decrease in TNT formation upon suppressing the mTOR signalling by pharmacological inhibitors such as Metformin and Everolimus." (PMID 30409198, 2018). "Their anti-tumor mechanisms could involve induction of cancer cell apoptosis and activation of PI3K/AKT, mTOR and NF-KB signaling pathways." (PMID 29732005, 2018). "Human cancers show activation of the PI3K, Akt, and mammalian target of rapamycin (mTOR) pathway." (PMID 29983865, 2018). "Given the wide network of mTORC1 targets that are involved in cancer, it is surprising that mTOR inhibitors are not more widely used for treating cancer." (PMID 29301334, 2018). "For example, the mTOR signaling pathway is often constitutively active in cancer, promoting growth signaling irrespective of metabolic environments." (PMID 29462149, 2018). "In addition, an overview of the PI3K/AKT/mTOR network and interactions of its downstream components with PIM kinases in different cancer cells is presented, specially focusing the OC cells." (PMID 29401696, 2018). "Given the broad range of cancerous attributes that are promoted by mTOR, it is not surprising that cancer cells hijack the mTOR pathway as a mechanism to drive their progression." (PMID 29301334, 2018). "In addition, ISLA reduced the levels of pro-angiogenic factors such as MMP-9, PlGF, and VEGF in HT1080 CM via suppression of the HIF-1α/Akt/mTOR pathway, supporting the anti-angiogenic activity of ISLA in cancer cells." (PMID 30618749, 2018). "Thus, miR-495-3p inhibits MDR by regulating mTOR activity and autophagy, providing further evidence that the appropriate level of autophagy is essential for the maintenance of MDR in cancer." (PMID 30341283, 2018). "NVP-BEZ235, a dual PI3K/mTOR inhibitor, couldinhibit the activity of PI3K-Akt-mTOR pathwayand the proliferation of OS cancer cells effectively." (PMID 29535821, 2018). "In this review, we describe the role of mTOR in tumor and non-tumor cells in order to better analyze the mechanisms of cancer progression and metastasis as well as drug resistance development." (PMID 30126252, 2018).
cancer (continued). "We hypothesized that AGN exerts cytotoxicity by inhibiting PI3K/AKT/mTOR and MAPK signaling, downstream pathways of BCR, the dysregulation of which has been shown to contribute to the formation of various human cancers, including DLBCL26." (PMID 30002430, 2018). "In this sense, targeting OGT in cancer cells and/or adapting patients to low caloric diet could increase the efficiency of anti-PI3K/AKT/mTOR therapeutic strategies and foil drug resistance." (PMID 30356686, 2018). "Although rapamycin and its analogues (rapalogs) have shown clinical efficacy in a subset of cancer types, they do not fully exploit the potential anti-tumor activity of the mTOR-targeting drugs, to some extent because of their pharmacodynamics." (PMID 29351204, 2018). "Next, they demonstrated that the lack of senescence induction observed in HPV-positive cancer cells cultured under hypoxic conditions is because of impaired mTOR signaling." (PMID 29637045, 2018). "Although some data have suggested that NRF2 promotes mTOR pathway in cancer cells, we did not detect any mTOR activity when NRF2 was present during oxidative stress (unpublished data)." (PMID 29510589, 2018). "Taken together, DHA-induced cancer cell apoptosis may be mediated with excess ROS, activation of MAPKs, MKP-1, STAT3-NF-κB, Akt, and mTOR signaling and increased in cAMP/cGMP, TLR-4, and PPAR-α." (PMID 30400136, 2018). "Based on the fact that the combination therapeutic strategy showed great effect in TNBC, we inferred that it would also be effective in those cancers showing the same molecular profiles as TNBC, especially high expression of MCL-1 controlled by AKT/mTOR pathway." (PMID 29374168, 2018). "Moreover, inhibition of mTOR, which is downstream of PI3K/Akt, by prolonged rapamycin treatment, delays cancer formation in aged mice." (PMID 29697773, 2018). "Our findings provided evidences that the combination of BH3 mimetics with mTOR inhibitors can lead to efficient apoptosis in TNBC; it could be a promising therapeutic strategy to treat these refractory cancers in the future." (PMID 29374168, 2018). "Further mechanism exploration demonstrated that EBV-miR-BART1-5P has important roles in cancer cell glucose metabolism and angiogenesis by inhibiting AMPKα1 and PTEN, which provides a molecular basis for the regulation of AMPK/mTOR/HIF1 and PTEN/FAK, Shc, AKT pathways, respectively." (PMID 30557400, 2018). "EMT is important in cancer progression and metastasis and several studies have shown that EMT is disrupted following inhibition of PI3K/AKT/mTOR, although the exact mechanism by which mTOR signaling directly modulates EMT is not clear across all pathologic processes." (PMID 29518028, 2018). "In contrast, oncogenes may be activated by mTOR, class I PI3K, and AKT, resulting in the suppression of autophagy and enhancement of cancer formation." (PMID 30400561, 2018). "In many cancers, the synthesis of HIF-1α is strictly related to mTOR activity." (PMID 30510924, 2018). "Notably, in some cancers, translation of MCL-1 is cap-dependent, which means inhibition of mTOR would suppress MCL-1 by blocking cap-dependent translation." (PMID 29374168, 2018). "Besides, it has been demonstrated that when inhibiting the mTOR signaling pathway, the CSC properties are reduced and the invasion potential is restrained in some of the cancer types." (PMID 29932116, 2018). "This cytostatic nature of mTOR inhibitors is a principal reason why rapalogues have had limited clinical success in the cancer setting, where the lack of cytotoxicity leads to acquired drug resistance." (PMID 30308940, 2018). "While mTOR has been shown to regulate STAT3/p63/Notch signaling in cancer cells, the molecular details of STAT3 modulation of AMPKα and/or mTOR activity remain unknown." (PMID 28686615, 2017).
cancer (continued). "In addition, recent evidence indicates that 6-MP inhibits the phosphatidylinositol 3 kinase (PI3K) / mammalian target of rapamycin (mTOR) signaling pathway, suggesting that these drugs might interfere with metabolic checkpoints and impact metabolic reprogramming in normal T cells and cancer." (PMID 28574837, 2017). "Although some of the signaling proteins downstream of IGF1R, such as Akt, mTOR and AMP-activated protein kinase (AMPK), have a pivotal role in cancer cell metabolic reprogramming, the possible role of IGF1R as a mediator of the Warburg effect has not been clearly established." (PMID 28969033, 2017). "The phosphoinositide 3-kinase/protein kinase B/mammalian target of rapamycin (PI3K/Akt/mTOR) pathway, which is downstream of EGFR signaling, may also play an important role in cancer." (PMID 27935858, 2017). "The second generation ATP-competitive kinase-targeting mTOR inhibitors (OSI-027, INK-128, and CC-223) inhibit both mTORC1 and mTORC2 complexes and are currently being tested in clinical studies for cancer treatment." (PMID 29088817, 2017). "ROS induced by therapeutic agent contributes to the formation of the intramolecular disulfide bond of Akt and the increase of the phosphorylation level of Akt, which results in the activation of Snail, mTOR, and ERK, and the induction of EMT and drug resistance of cancer cells." (PMID 29262602, 2017). "Hence we investigate the impact of conversion to mTOR inhibitors together with CNI minimization on the allograft outcome and patient survival in kidney transplant recipients who developed de novo cancers." (PMID 28160552, 2017). "An inhibition of mTOR by RARRES1 expression demonstrate that RARRES1 modulates autophagy and its inhibition in PCa cells may lead to cancer progression." (PMID 28678839, 2017). "Although there were fewer episodes of cancer recurrence (5.4% vs 11.9%) in the mTOR inhibitor group than in the non-conversion group, the difference was not statistically significant." (PMID 28160552, 2017). "It seems therefore possible to speculate that γ-tocotrienol induces opposite effects in cancer and normal (or pseudo-normal) cells in agreement with the established perturbation of PI3K/Akt/mTOR signaling pathway in cancer cells." (PMID 29156559, 2017). "Regarding signaling, AF inhibited the phosphorylation of intracellular molecules, including Akt, mTOR, p70S6K, and 4E-BP1, suggesting that AF may be a valuable anti-cancer drug." (PMID 28207754, 2017). "Although not much is known about the effect of mTOR inhibitors on UV-induced carcinogenesis, it is recognized that rapamycin prevents cancer by other carcinogens and spontaneous cancer in animals and humans." (PMID 29312653, 2017). "As mTOR inhibition results in ULK1 and autophagy activation, this might give an advantage to cancer cells in order to survive drug treatment." (PMID 29233870, 2017). "Notably, the number of TFs dysregulated by PI3K pathway alterations varied widely across different cancers (9 in HNSC, 65 in BRCA and 63 in UCEC), with striking changes in ErbB/MAPK, mTOR, HIF-1, VEGF and PI3K-Akt pathways." (PMID 28139702, 2017). "The phosphoinositide 3-kinase (PI3K)–Akt–mammalian target of rapamycin (mTOR) pathway plays a pivotal role in cancer cell proliferation, and mutations in the PIK3CA gene are commonly found in various cancers regardless of histological subtypes." (PMID 28068934, 2017). "In cancer, mTOR activation, induction of the EIF complex, and cooperation between these two pathways are known to be important for initiation of particular types of protein synthesis that influence cancer progression or confer resistance to treatment." (PMID 29221196, 2017). "Although mTOR plays important roles in regulating cancer cell growth, metabolism and protein synthesis, the allosteric mTOR inhibitor rapamycin (sirolimus) fails to be approved as an anti-cancer agent due to its immunosuppresive effects." (PMID 28592260, 2017).
cancer (continued). "Inhibition of the MTOR pathway phenocopied inhibition of the MEK-ERK or AKT pathways, suggesting that MTOR is a downstream effector of both the MEK-ERK and AKT pathways for actin reorganization in Rb-depleted hypoxic cancer cell lines." (PMID 28798482, 2017). "In sum, our metabolic and transcriptomic analyses have revealed that depletion or inhibition of CDK4/6 in cancer cells leads to de novo addiction to MYC, and, as likely downstream consequences, also to glutaminase and mTOR signaling, as well as to a compromised adaptation to hypoxia." (PMID 28978620, 2017). "Certain inhibitors of mTOR and PI3K have been approved for the treatment of some types of cancer, and these and other inhibitors of mTOR and PI3K are under investigation in a variety of cancer settings." (PMID 29137436, 2017). "To figure out how MVP translocates to the cell surface, we treated Huh7 cells with some chemical inhibitors of cancer cell signaling pathways, and found that U0126 (ERK inhibitor) and rapamycin (mTOR inhibitor) obviously decreased cell surface expression of MVP." (PMID 29038587, 2017). "Indeed, in PC3, DU145, MDA-MB-231 and BT-549 cancer cells RAD001 downregulated both SK1 and VEGF through mTOR inhibition." (PMID 28615679, 2017). "The establishment of markers to determine the activity of mTOR in AR- DLBCL and other AIDS related cancers will allow a rational approach to the selection of patients who may further benefit from mTOR inhibition." (PMID 28192480, 2017). "Here, we demonstrate that CC-115 is a selective mTOR kinase/DNA-PK dual inhibitor with excellent kinase selectivity, even over closely related ATR, ATM and PI3K-alpha and with potent inhibitory activity across many cancer cell lines." (PMID 29088817, 2017). "Recently, it is also suggested that cancer and T cells may share similar requirements for BCAA catabolism that regulates the mTOR signaling." (PMID 28447025, 2017). "In particular, MTOR and AMPK are hypothesized to be concurrently activated in cancer cells by amino acids recycled from the stroma." (PMID 28969664, 2017). "More patients (7/59, 11.9%) in the non-conversion group developed recurrence of cancers than mTOR inhibitor group (3/56, 5.4%)." (PMID 28160552, 2017). "Inhibition of HSP90 target proteins such as AKT and phospho-AKT, which are frequently active or overexpressed in many cancer cells, including GBC, affect the PI3K/AKT/mTOR signaling pathway which plays an important role in regulating cell cycle progression, apoptosis and cell survival." (PMID 28412732, 2017). "More patients in the non-conversion group developed recurrence of cancers than mTOR inhibitor group but statistically not significant." (PMID 28160552, 2017). "Analysis with data from the Cell Miner Tool in 60 cancer cell lines indicated that although rapamycin activity was correlated with levels of MTOR, it is not influenced by DDIT4 expression." (PMID 28484222, 2017). "In the context of a progressing cancer cell, PI3K/Akt/mTOR promotes survival and proliferation when conditions are fertile for cell proliferation, whereas AMPK serves as a sensor of nutrient starvation and ensures optimization of energetic sources when a cancer cell requires saving energy." (PMID 29230384, 2017). "Furthermore, PPAR-γ agonists downregulate key pathways of the insulin/IGF axis, such as PI3K/mTOR, MAPK, and GSK3β/Wnt/β-catenin cascades, which regulate cancer cell growth, proliferation, cell reprogramming, and differentiation." (PMID 28275367, 2017). "The mTOR protein is a down-stream effector of the PI3K-Akt signaling pathway and considered a Ser/Thr protein kinase; it has received considerable attention as a possible target for cancer treatment." (PMID 29233126, 2017).